BRD7 (bromodomain containing 7)
Diseases named in the same sentence as BRD7 in open-access papers (continued):
Sharing a sentence is not in itself a finding about the gene and the disease.
ovarian carcinoma (7 papers, 2016 to 2025). A malignant neoplasm originating from the surface ovarian epithelium. "Endometrial cancer and ovarian cancer exhibit low expression of BRD7, which is correlated with down-regulated beta-catenin accumulation." (PMID 30406031, 2018). "In ovarian cancer, BRD7 expression is decreased in high-grade serous carcinoma relative to normal or low-grade carcinoma." (PMID 30406031, 2018). "A previous report showed that decreased BRD7 expression might play a crucial role in the aggressive behavior of high-grade ovarian tumors and may potentially serve as a prognostic marker for ovarian cancer." (PMID 26919247, 2016). "Bromodomain containing 7 (BRD7) is a transcription factor that acts as a tumour suppressor protein in various cancers, including in ovarian cancer." (PMID 33447132, 2020). "Overexpression of BRD7 in A2780 and SKOV3 ovarian cancer cell lines reduces cell survival and increases apoptosis." (PMID 32992509, 2020).
Obesity (6 papers, 2016 to 2026). Accumulation of substantial excess body fat. "Downregulation of BRD7 has been shown to be associated with many pathophysiological conditions, including obesity, diabetes, and cancer." (PMID 32992509, 2020). "Of these, only ARAP1 and BRD7 were affected by globally significant SNPs (i.e., rs8050136 and rs11603334) that had previously been associated with both obesity and type 2 diabetes." (PMID 29081791, 2017). "BRD7 deficiency exacerbated weight gain and BRD7 upregulation prevented the development of obesity." (PMID 30926848, 2019). "Therefore, we sought to investigate whether BRD7 deficiency in combination with obesity might have a synergistic effect in disturbance of glucose homeostasis." (PMID 27444544, 2016). "Here, we review the involvement of BRD7 in a variety of pathophysiological conditions, with a focus on glucose homeostasis, obesity, and cancer." (PMID 32992509, 2020). "BRD7 plays an important role in the pathogenesis of many cancers and, more recently, its roles in the regulation of metabolism and obesity have also been highlighted." (PMID 32992509, 2020). "While previous studies showed that BRD7 plays a role in insulin signaling and glucose homeostasis, the exact function of BRD7 in the development of obesity was unclear." (PMID 30926848, 2019). "Our work highlights BRD7 as a potential therapeutic target for the prevention of obesity and treatment for type 2 diabetes." (PMID 30926848, 2019). "This makes it difficult to study the consequences of BRD7 downregulation once obesity has already developed." (PMID 30926848, 2019). "In conclusion, we have found that BRD7 upregulation protects against the development of obesity and also restores impaired glucose homeostasis once obesity has been established." (PMID 30926848, 2019). "In this report, we utilized knockout and transgenic mouse models to investigate how BRD7 affects the development of obesity and glucose homeostasis." (PMID 30926848, 2019). "We have documented that acute up‐regulation of BRD7 in the liver of obese mice reinstates XBP1s nuclear translocation and re‐establishes glucose homoeostasis in obesity." (PMID 27444544, 2016). "We have previously reported HFD‐induced obesity leads to reduction in hepatic BRD7 expression levels." (PMID 27444544, 2016). "Furthermore, literature has also indicated that BRD7 is involved in regulating glucose metabolism and insulin signalling pathways, thereby influencing processes such as obesity and embryonic development." (PMID 41510594, 2026). "BRD7 is a member protein of the bromodomain-containing protein family and plays a crucial role in the pathogenesis of cancers and the regulation of inflammation, metabolism, and obesity." (PMID 37197658, 2023). "Upregulation of BRD7 in the liver protects against the development of obesity." (PMID 32992509, 2020). "Likewise, upregulation of BRD7 improves insulin signaling in obesity, but inhibits PI3K activity in a cancerous state." (PMID 32992509, 2020). "Understanding whether long-term overexpression of BRD7 in the liver is beneficial for glucose homeostasis would highlight its potential as a therapeutic target for the treatment of obesity and type 2 diabetes." (PMID 30926848, 2019). "Reduction in hepatic BRD7 expression levels has been observed in obese and type 2 diabetic mice in our previous study 16, implicating its potential role in the development of glucose intolerance and insulin resistance in obesity." (PMID 27444544, 2016). "Given that our BRD7+/− and LBKO mice displayed increased weight gain and BRD7 upregulation significantly improved glucose homeostasis in AAV-Cre-injected BRD7 Tg+/− mice, we sought to investigate whether the early upregulation of BRD7 could also protect against the development of obesity." (PMID 30926848, 2019).
Obesity (continued). "This implies that reduced levels of hepatic BRD7 per se may not directly lead to the development of type 2 diabetes, but preventing the decrease of BRD7 caused by obesity is enough to stop the progression of type 2 diabetes." (PMID 30926848, 2019).
osteosarcoma (6 papers, 2014 to 2024). A usually aggressive malignant bone-forming mesenchymal neoplasm, predominantly affecting adolescents and young adults. "Increased interaction between BRD7 and cdh1 or cdc20 leads to ubiquitin-mediated degradation of BRD7 in osteosarcoma." (PMID 32992509, 2020). "Inhibiting APC/C activity, which participates in promoting osteosarcoma cell growth and tumor formation, decreases degradation of BRD7 and reduces the proliferation of cells in osteosarcoma." (PMID 32992509, 2020). "Although BRD7 has been reported to be mainly localized in the nucleus, we found that BRD7 was mainly localized in the cytoplasm of osteosarcoma tissues." (PMID 24840027, 2014). "Taken together, these results indicate that the degradation of BRD7 by APC/C E3 ligase plays key roles in osteosarcoma." (PMID 24840027, 2014). "The growth of transfectants with BRD7-WT was much slower than that of transfectants with vectors, supporting that BRD7 functions as a tumor suppressor in osteosarcoma." (PMID 24840027, 2014). "In this study, we found that APC/Ccdh1 and APC/Ccdc20 directly bind and degrade BRD7, a finding that is clinically relevant because a strong inverse correlation between the expression levels of BRD7 and Cdh1 or Cdc20 was observed in patients with osteosarcoma." (PMID 24840027, 2014). "Conversely, when the APC/C complex is inhibited by small-molecule inhibitors, such as pro-TAME, the BRD7 protein is stabilized and suppresses osteosarcoma tumor progression." (PMID 24840027, 2014). "Moreover, lower BRD7 expression was also identified as an indicator of poor prognosis in patients with osteosarcoma." (PMID 26919247, 2016). "Moreover, BRD7 is a tumor suppressor in osteosarcoma, and the BRD7 mutant resistant to degradation by APC/C is more efficient than the wild-type protein at suppressing proliferation, colony formation, and tumor growth of osteosarcoma in vitro and in vivo." (PMID 24840027, 2014). "Our results showed that BRD7 may be regulated by APC/C E3 ligase during mitotic exit and that the cell cycle profile was significantly changed by knockdown of BRD7 in osteosarcoma cells." (PMID 24840027, 2014). "Importantly, the BRD7 protein levels are inversely correlated with Cdh1 or Cdc20 protein levels in osteosarcoma clinical samples." (PMID 24840027, 2014). "Interestingly, BRD7 expression in osteosarcoma tissue was largely correlated with patients' survival time (p=0.020)." (PMID 24840027, 2014). "Furthermore, there is a strong inverse correlation of protein levels between BRD7 and Cdh1 or Cdc20, and lower BRD7 expression is an indicator for poor prognosis in patients with osteosarcoma." (PMID 24840027, 2014). "Taken together, the data show that BRD7 may be degraded by APC/C E3 ligase during mitotic exit in osteosarcoma cells." (PMID 24840027, 2014). "Furthermore, the lower level of BRD7 correlates with poor clinical outcome in patients with osteosarcoma." (PMID 24840027, 2014). "Furthermore, an inverse correlation was observed between the protein levels of BRD7 and Cdh1 or Cdc20 (p<0.001, χ2 tests), demonstrating that Cdh1 and Cdc20 may also negatively regulate BRD7 protein in osteosarcoma tissues." (PMID 24840027, 2014). "In human osteosarcoma tissues, the anaphase-promoting complex/cyclosome (APC/C), a complex of E3 ligases that mediates the ubiquitination of proteins during mitosis, targets BRD7 for ubiquitin-mediated degradation through its co-activators cdh1 and cdc20." (PMID 32992509, 2020). "In this report, we demonstrate that BRD7, as a new substrate of APC/C-E3 ligase during the cell cycle, is a tumor suppressor in osteosarcoma, and this APC/C-BRD7 pathway may provide a potential therapeutic target for treating osteosarcoma." (PMID 24840027, 2014). "Lower or no BRD7 expression indicated a shorter overall survival time (OS) in patients with osteosarcoma compared with higher BRD7 expression." (PMID 24840027, 2014).
osteosarcoma (continued). "Moreover, the BRD7 mutant that was resistant to APC/C degradation was more efficient at suppressing proliferation, colony formation and tumor growth in osteosarcoma, and a lower level of BRD7 predicts poor prognosis in patients with osteosarcoma." (PMID 24840027, 2014).
endometrial cancer (4 papers, 2018 to 2023). Primary or metastatic malignant neoplasm involving the endometrium (mucous membrane that lines the endometrial cavity). "Increased expression of miR-200c in endometrial cancer tissues reduces the expression of BRD7, which is a potential tumor suppressor." (PMID 32760226, 2020).
Hyperglycemia (4 papers, 2017 to 2020). An increased concentration of glucose in the blood. "In conclusion, inhibition of BRD7 appeared to protect against hyperglycaemia‐induced cardiomyocyte apoptosis by inhibiting ER stress signalling pathway." (PMID 27957794, 2017). "However, knocking down BRD7 by BRD7-specific shRNA in mice after challenging them with a high-fat diet leads to hyperglycemia." (PMID 32992509, 2020). "Additionally, BRD7‐ER stress signalling pathways play an essential role in hyperglycaemia‐induced cardiomyocyte apoptosis." (PMID 27957794, 2017).
lung carcinoma (4 papers, 2011 to 2022). "Data indicated that higher USP24 level led poor prognosis significantly, but only slightly relevance in BRD7 level in lung cancer progression." (PMID 33257797, 2020). "Next, we studied the protein stability of BRD7 in the overexpression of GFP-USP24-WT or GFP-USP24-CA with cycloheximide treatment for different time course in H1299 lung cancer cells." (PMID 33257797, 2020). "Following IR, a colony forming assay showed that IFN-γ treatment decreased clonogenic cell survival in A549 lung cancer cells but that BRD7 depletion inhibited the decrease in clonogenic cell survival induced by IFN-γ treatment." (PMID 26802028, 2016). "To investigate whether BRD7 acts as critical regulator of XAF1 in lung cancer cells, we examined migration and invasion by transfecting BRD7 siRNAs into cells overexpressing XAF1." (PMID 26802028, 2016). "In addition to the degree of differentiation and extent of lymphatic metastasis, BRD7 expression is correlated with TNM stage, which indicates that BRD7 may be related to the occurrence, development, and metastasis of lung cancers." (PMID 22008115, 2011). "USP24 knockdown (KD) in H1299 lung cancer cells and U2OS bone cancer cells decreased levels of the BRD-containing proteins including BRG1, BRD7, BRD1, BRD3, GCN5, PCAF, and TIF1α." (PMID 33257797, 2020). "For example, BMPR2, BRD7, PRKAG2, PRKAR1A and PPP2R2A (PP2A Bα subunit B55α), which are differentially expressed between group V (H+V−S+[M/T]) and groups II/IV (H+V+S−/H+V−S+[M]), play roles in tobacco-mediated lung diseases and lung cancers." (PMID 35642061, 2022). "XAF1 decreased migration and invasion ability in lung cancer cells, although the increase in XAF1 expression, migration and invasion was not reduced by BRD7 depletion." (PMID 26802028, 2016). "In lung cancer cells, XAF1 tumor suppressor activity was decreased by BRD7 knockdown, and inhibition of tumor growth by IFN-γ did not appear in BRD7-depleted xenograft tumors." (PMID 26802028, 2016).
male infertility (4 papers, 2016 to 2024). The inability of the male to effect fertilization of an ovum after a specified period of unprotected intercourse. "The lack of an association of BRD7-linked rare and common variants with spermatogenic failure implied a limited contribution of the BRD7 gene to spermatogenic efficiency and susceptibility to male infertility in humans." (PMID 34470615, 2021). "Rush is highly expressed in the immature Sertoli cells of rabbit testis after birth and before puberty, and the deficiency of BRD7 results in impaired spermatogenesis and male infertility in mice." (PMID 33398438, 2021). "In summary, this study is the first to investigate the association of the BRD7 gene with spermatogenic failure and male infertility in humans." (PMID 34470615, 2021). "Our results implied a limited contribution of the BRD7 gene to susceptibility to spermatogenic failure and male infertility in humans." (PMID 34470615, 2021). "BRD7 deficiency can lead to a blockage of spermatogenesis and male infertility in mice, therefore, we associated male infertility resulting from BRD7 disruption with human idiopathic azoospermia." (PMID 26878912, 2016). "In this case, it would be interesting to determine whether the BRD7 gene is associated with the risk of spermatogenic failure and male infertility in humans." (PMID 34470615, 2021). "To confirm that the phenotype of male infertility and abnormal spermatogenesis specifically resulted from BRD7 deficiency in the sperm cells of testes, we further constructed germ-cell-specific BRD7 null mice by crossing BRD7-LoxP mice with Stra-Cre mice." (PMID 26878912, 2016). "Taken together, our results demonstrate that BRD7 is involved in male infertility and spermatogenesis in mice, and BRD7 defect might be associated with the occurrence and development of human azoospermia." (PMID 26878912, 2016). "Knockout study has illustrated the indispensable role of BRD7 in spermatogenesis in which depletion of BRD7 leads to arrest of spermatogenesis and male infertility in mice." (PMID 38992588, 2024). "A recent model of Brd7-knockout mice presented azoospermia and male infertility, implying the potential role of BRD7 in spermatogenic failure in humans." (PMID 34470615, 2021). "Using these BRD7-KO mice, we found that the disruption of BRD7 in homozygous (BRD7−/−) mice results in complete male infertility and blocking of spermatogenesis, which sheds insights into BRD7’s in vivo function." (PMID 26878912, 2016). "Remarkably, BRD7 is highly expressed in the pachytene stage to the round spermatid stage during mouse spermatogenesis, which is similar to that in humans, and Brd7−/− male mice present AZ and male infertility." (PMID 34470615, 2021). "Collectively, our findings imply a limited contribution of BRD7 to human male infertility." (PMID 34470615, 2021). "Together, our results indicate that the loss of BRD7 led to male infertility and the absence of sperm in the epididymis." (PMID 26878912, 2016). "Complete male infertility and defects in sperm cells in the epididymis were observed in these male mice (data not shown), supporting that a BRD7 deficiency in germ cells is the primary cause of male infertility and abnormal spermatogenesis." (PMID 26878912, 2016). "Moreover, BRD7 disruption does not affect the sexual response, hormone levels and mating ability of mice; however, the testis was underdeveloped and no mature sperm was observed in the testis epididymis, which may cause male infertility in KO mice." (PMID 26878912, 2016).
type 2 diabetes (4 papers, 2016 to 2020). "Nonetheless, the body of published data so far suggest that BRD7 can be an attractive therapeutic target for treating patients with type 2 diabetes and cancer." (PMID 32992509, 2020). "We have previously reported that hepatic BRD7 expression levels are significantly reduced in obese and type 2 diabetic mice and acute overexpression of BRD7 in the liver through the tail vein injection of adenovirus that expresses BRD7 re‐establishes glucose homoeostasis." (PMID 27444544, 2016). "They showed that the interaction of BRD7 with VDR ultimately leads to inhibition of BRD9 activity in β cells, which in turn reverses β cell dysfunction and reduces blood glucose levels in type 2 diabetic mouse models." (PMID 30926848, 2019).
Burkitt lymphoma (3 papers, 2023 to 2024). A rare form of malignant mature B-cell non-Hodgkin lymphoma. "Based on the chromatin immunoprecipitation (ChIP) sequencing of endogenous BRD7 in Burkitt lymphoma cells, we found that EBV drove BRD7 to regulate cellular and viral genomic loci, including the transcriptional activation of c-Myc, a recently reported regulator of EBV latency." (PMID 36728436, 2023). "Similarly, in the Burkitt lymphoma cells, bromodomain-containing protein 7 is hijacked by EBV to synergistically maintain viral latency through its encoded EBNA1 binding to host BRD7 to coordinate chromatin remodeling, leading to transcriptional activation of c-Myc." (PMID 38572321, 2024). "In another study, EBNA1 was found to target c-Myc by chromatin immunoprecipitation (ChIP) sequencing of endogenous bromodomain-containing protein 7 (BRD7) in Burkitt lymphoma(BL), thereby regulating the viral infection status by coordinating with host BRD7." (PMID 38482011, 2024).
cervical cancer (3 papers, 2018 to 2025). A primary or metastatic malignant neoplasm involving the cervix. "In our study, high expression of BRD7 was associated with improved DFS in cervical cancer patients." (PMID 30406031, 2018). "In conclusion, AGR2 and BRD7 expression have prognostic significance in cervical cancer and provide opportunities for improved treatment options." (PMID 30406031, 2018). "Furthermore, we demonstrated for the first time that low expression of AGR2, high expression of BRD7 or POM121 combined with low expression of PAUF predict delayed recurrence in cervical cancer patients." (PMID 30406031, 2018). "Cox regression analysis confirmed that BRD7 and its combination with PAUF and other PAUF-related proteins is an important prognostic indicator in cervical cancer." (PMID 30406031, 2018). "The identified proteins (AGR2, BRD7, and POM121) were differentially expressed according to cell type, clinical prognostic factors, and resistance to radiation therapy in cervical cancer patients." (PMID 30406031, 2018). "Furthermore, we demonstrated that AGR2, BRD7, and POM121 protein expression had prognostic value when combined with PAUF expression using an analysis of a large cohort of cervical cancer patients." (PMID 30406031, 2018).